SVIP (small VCP interacting protein)
Description:
Negative regulator of the ER-associated degradation pathway (ERAD) of misfolded proteins. It competes with AMFR/gp78 for binding VCP/p97, and inhibits AMFR/gp78-VCP/p97 complex formation that is required for degradation of ERAD substrates. Involved in the regulation of adrenal cortisol and dehydroepiandrosterone (DHEA) biosynthesis.
Synonyms: DKFZp313A2432
Tractability: Antibody: its Gene Ontology location is reachable by antibodies, with high confidence; UniProt places it where antibodies can reach, with medium confidence. PROTAC: ubiquitination databases record sites on it; its protein half-life has been measured.
Gene: Protein-coding gene on chromosome 11 (22,813,799 to 22,830,299, reverse strand). Ensembl gene ENSG00000198168.
Subcellular location: Membrane; Smooth endoplasmic reticulum membrane; Golgi apparatus membrane; Cell membrane; Lysosome membrane
Pathways (Reactome):
Immune System: Neutrophil degranulation
Gene Ontology:
Molecular function: ATPase binding; protein binding
Biological process: negative regulation of ERAD pathway; negative regulation of protein-containing complex assembly; negative regulation of retrograde protein transport, ER to cytosol; positive regulation of autophagy; positive regulation of protein lipidation; negative regulation of VCP-NPL4-UFD1 AAA ATPase complex assembly
Cellular component: endoplasmic reticulum membrane; extracellular exosome; lysosomal membrane; membrane; Golgi membrane; plasma membrane; secretory granule membrane; smooth endoplasmic reticulum membrane; tertiary granule membrane
Genetic constraint (gnomAD): Loss-of-function variants: 5 observed, 4.12 expected, observed/expected ratio (o/e) 1.21, 90% interval 0.6 to 1.89. That is too few expected variants to judge how well the gene tolerates losing a copy. Missense variants: 69 observed, 59.25 expected, observed/expected ratio (o/e) 1.16, 90% interval 0.96 to 1.42. Synonymous variants: 28 observed, 22.86 expected, observed/expected ratio (o/e) 1.22, 90% interval 0.91 to 1.67.
Homologues: Orthologues: chimpanzee SVIP (100% identical), macaque SVIP (100% identical), dog SVIP (92% identical), pig SVIP (91% identical), guinea pig SVIP (90% identical), mouse Svip (81% identical), rat Svip (77% identical).
Diseases named in the same sentence as SVIP in open-access papers:
SVIP is named in the same sentence as 47 diseases in open-access papers, as found by Europe PMC text mining. Sharing a sentence is not in itself a finding about the gene and the disease. The quoted sentences say what the papers report.
glioma (7 papers, 2011 to 2024). A benign or malignant brain and spinal cord tumor that arises from glial cells (astrocytes, oligodendrocytes, ependymal cells). "As SVIP was identified as an androgen-dependent gene and reported to be associated with tumorigenesis of both prostate cancer and glioma, we have investigated the SVIP expression in various cancers, with a particular focus on breast cancer due to its estrogen dependency." (PMID 37408196, 2023). "As SVIP was identified to be related to the tumorigenesis of breast, glioma, and prostate cancer, we chose to study SVIP expression with a focus on pancreatic cancer." (PMID 39473740, 2024). "Recently, SVIP (small VCP/97-interacting protein), an endogenous ERAD inhibitor, has been implicated in cancer progression, especially in glioma, prostate, and head and neck cancers." (PMID 37408196, 2023). "Taken together, these results indicated that SVIP was downregulated by AR and also explained that its expression was low in high-grade glioma tissue samples." (PMID 28423563, 2017). "Consistent with the Western blot result, the immunohistochemistry staining showed lower expression of SVIP in high-grade gliomas than in the NC, and a reverse trend of AR expression in the nucleus was observed." (PMID 28423563, 2017). "Our results indicate that the role of AR and SVIP in the pathogenesis of different types (subtypes) of gliomas requires being defined discretely." (PMID 28423563, 2017). "A 95% downregulation of SVIP expression, from NC to high-grade gliomas (WHO III and IV) was observed; consecutively, the AR expression increased as the tumor grade progressed, irrespective of the gender." (PMID 28423563, 2017). "All these results illustrated that the decreased SVIP expression, as well as increased AR expression, in glioma tissues correlated with gliomas progressing from low to high grades." (PMID 28423563, 2017). "SVIP has also been identified as an androgen-regulated gene in prostate cancer and glioma." (PMID 37408196, 2023). "Similarly, the decreased SVIP expression, as well as increased AR expression, in glioma tissues correlated with gliomas progressing from low to high grades." (PMID 37408196, 2023). "Moreover, this androgen-mediated downregulation of SVIP was also reported to be present in the glioma cells and involved in the cell proliferation regulation of glioma cells with wild-type p5314." (PMID 35042898, 2022). "Furthermore, the expression level of AR, analyzed by WB and IHC, in tumor tissue was closely correlated with the malignancy of glioma, whereas SVIP protein expression showed an opposite trend." (PMID 28423563, 2017). "Thus, in the current study, AR and SVIP expression in each grade glioma tissue are mostly compared with normal tissues, instead of peritumoral tissues." (PMID 28423563, 2017).
glioma (continued). "Moreover, the AR expression is increased while SVIP expression is decreased in tumor tissue of glioma patients, which is in agreement with the progressing WHO grades." (PMID 28423563, 2017). "Furthermore, it has been proved that SVIP is down-regulated as well as AR is up-regulated in glioma cell lines with R1881 treatment." (PMID 28423563, 2017). "In addition to the prognostic and therapeutic molecular studies, it is important to determine the presence and function of it has been proven to exist in two different tumors (glioma and prostate cancer) SVIP and its interacting protein p97/VCP in pancreatic cancer types." (PMID 39473740, 2024). "In addition to our knowledge, we found one of the molecular mechanisms of SVIP-controlled PTENwt-dependent IGFBP-2 regulation in glioma, which provides the basis for IGFBP-2 as a marker indicating PTEN status, tumor progression, recurrence and survival of high-grade glioma." (PMID 39138166, 2024). "Moreover, SVIP has been defined as an androgen-regulated gene in glioma and prostate cancer." (PMID 39473740, 2024). "Conversely, in high-grade glioma tissues, there was a notable upregulation in STUB1 expression, whereas SVIP expression exhibited a decline." (PMID 39138166, 2024). "It has been proven that SVIP is downregulated, but other ERAD components and androgen receptors (AR) are upregulated in glioma and androgen-dependent prostate cancer cell lines with R1881 treatment." (PMID 37408196, 2023). "To clarify this issue, we studied the effects of SVIP knockdown on LC3II accumulation in three more cell lines, including U87 and U251, two glioma cell lines, and SKBR3, a breast cancer cell line." (PMID 21909394, 2011). "Furthermore, synthetic androgen treatment downregulated SVIP levels but upregulated other ERAD components, including gp78, p97/VCP, and Derlin1, enhancing ERAD proteolytic activity both in glioma and prostate cancer cells." (PMID 37408196, 2023).
prostate carcinoma (5 papers, 2017 to 2024). A carcinoma that arises from epithelial cells of the prostate gland. "In one experimental study, silencing the expression of the ERAD genes SVIP, gp78, and Hrd1 reduced the malignant transformation and migration of LNCaP prostate cancer cells." (PMID 39473740, 2024). "In cancer cells, SVIP was overexpressed in prostate cancer tissue, while its inhibition reduces migration and malignant transformation." (PMID 38283944, 2023). "Firstly, SVIP levels were downregulated after androgen treatment in prostate cancer cells, while other components of ERAD machinery were upregulated, which was found to be positively related to prostate tumorigenesis." (PMID 37408196, 2023). "Our results revealed that SVIP mRNA expression was upregulated in many cancer types, including adrenal, breast, and prostate cancers." (PMID 37408196, 2023). "In conclusion, our data suggests that silencing of Hrd1 and gp78 affect the proliferation rate, whereas Hrd1, gp78 and SVIP have role in malignant transformation of prostate cancer cells." (PMID 28091582, 2017). "In a prostate cancer tissue panel of patients we found the mRNA expression levels of Hrd1, gp78, and SVIP are upregulated in prostate cancer." (PMID 28091582, 2017). "ERAD genes found to be upregulated in prostate cancer tissues and silencing expression of Hrd1, SVIP, and gp78 reduced the in vitro migration and malignant transformation of LNCaP cells." (PMID 28091582, 2017). "Our data revealed that gp78, Hrd1, SVIP and AR showed increased expression (p < 0.05 for AR and p < 0.005 for gp78, Hrd1, SVIP) in prostate cancer tissues." (PMID 28091582, 2017). "We have previously reported androgen-dependent regulation of SVIP in prostate cancer." (PMID 37408196, 2023). "The expression of SVIP mRNA in tumor tissue was significantly higher than in normal tissue in most cancer types, including acute myeloid leukemia, breast, colon, liver, pancreas, thyroid, and prostate cancers." (PMID 37408196, 2023). "SVIP expression has been shown to be androgen-mediated downregulation in prostate cancer cells." (PMID 37374283, 2023).
breast carcinoma (4 papers, 2011 to 2024). "We examined the association between SVIP and breast cancer by performing comprehensive bioinformatics analysis on several large online databases and evaluated the expression profile in a variety of breast cancer cell lines." (PMID 37408196, 2023). "Furthermore, when the effect of SVIP expression on the overall survival of breast cancer patients was analyzed considering the breast cancer subtype, lower SVIP mRNA expression levels were associated with a worse prognosis in the luminal A, luminal B, and TNBC subtypes." (PMID 37408196, 2023). "Given the potential for the SVIP gene to be effective in breast cancer progression, functional analysis was performed in the next step." (PMID 37408196, 2023). "Given that SVIP expression is high in breast cancer cells, we evaluated the other functional key players of gp78-mediated ERAD." (PMID 37408196, 2023). "Another major outcome of our study was that we identified differences in SVIP protein expression levels between cell lines and in tumors in breast cancer." (PMID 37408196, 2023). "Strikingly, SVIP protein expression was much lower in total and all subtypes of breast cancer samples compared to normal tissues." (PMID 37408196, 2023). "We then explored the potential genetic alterations of SVIP in the context of breast cancer using the c-BioPortal online tool." (PMID 37408196, 2023). "The OncoPrint results showed that in 142 of 1084 breast cancer patients (13%), the SVIP gene had altered either amplification, deep deletion, high mRNA expression, or low mRNA expression; the most common alteration type was found to be high mRNA expression." (PMID 37408196, 2023). "Overall, our data reveal the differential expression and function of SVIP on breast cancer cell lines together with in silico data analysis." (PMID 37408196, 2023). "Here, the data of several RNA-sequencing (RNA-seq) and gene array studies were combined to evaluate the SVIP gene expression analysis on a variety of cancers, with a particular focus on breast cancer." (PMID 37408196, 2023). "Taken together, these results demonstrated that the SVIP mRNA expression was differentially regulated in most cancer types compared with normal tissues, particularly in breast cancer." (PMID 37408196, 2023). "Firstly, SVIP mRNA was found to be highly expressed in every clinicopathological stage of breast cancer compared with normal tissues using the UALCAN portal." (PMID 37408196, 2023). "To conclude, our data suggest that SVIP has a function in the regulation of cell proliferation and migration of breast cancer cells." (PMID 37408196, 2023). "Although several questions are still remaining, this manuscript sheds some light on the role of SVIP in breast tumorigenesis and indicates that SVIP has tumor-suppressor-like properties in breast cancer cells." (PMID 37408196, 2023). "While SVIP mRNA expression was much higher in breast cancer tissue compared to control tissue, SVIP protein level was found to be significantly lower." (PMID 37408196, 2023). "Our immunoblotting data confirmed that SVIP protein levels are significantly higher in breast cancer cell lines (MCF-7, T47D, ZR75-1, BT-474, SK-BR-3, and MDA-MB-231) compared to human mammary epithelial cells (MCF-10A)." (PMID 37408196, 2023). "As our analysis revealed that mRNA and protein expression levels of SVIP were different in breast tumor tissues compared to control tissues, we examined the expression level of SVIP protein in commercially available breast cancer cell lines." (PMID 37408196, 2023). "The expressions of p97/VCP and SVIP mRNA in tumor tissue were clearly higher than in normal tissue for most cancers, including prostate, pancreatic, acute myeloid leukemia, colon, rectal, and breast cancers." (PMID 39473740, 2024). "Similarly, with regard to SVIP, the findings of the current study are consistent with earlier results in human breast cancer." (PMID 39473740, 2024).
breast carcinoma (continued). "Our data revealing the differential expression and function of SVIP on breast cancer cell lines, together with in silico data, suggest that SVIP may have a tumor suppressor function in breast cancer progression." (PMID 37408196, 2023). "Importantly, our data revealed that SVIP protein levels in breast cancer tissues compared to normal tissues are low despite the increased mRNA levels." (PMID 37408196, 2023). "Another possible reason may be the enhanced endoplasmic reticulum stress conditions in breast cancer and the upregulation of Hrd1 and SVIP expressions by endoplasmic reticulum stress." (PMID 37408196, 2023). "Considering all this data suggesting that SVIP may play a role in tumor progression, we have first performed in silico analysis of SVIP expression on various cancers, with a particular focus on breast cancer." (PMID 37408196, 2023). "As SVIP mRNA is overexpressed in primary breast tumors compared to normal tissues, we next analyzed the expression of SVIP in distinct clinicopathological stages, parameters, and intrinsic subtypes of breast cancer." (PMID 37408196, 2023). "Importantly, the expression of SVIP was significantly upregulated in all the subtypes of breast cancer, namely luminal A, luminal B, HER2 positive, and triple-negative (basal-like) types." (PMID 37408196, 2023). "Results revealed that lower SVIP mRNA expression levels were associated with a worse prognosis of overall survival (OS) (HR = 0.74, p = 0.026) and distant metastasis-free survival (DMFS) (HR = 0.61, p = 0.00026) in breast cancer." (PMID 37408196, 2023). "SVIP mRNA was found to be highly expressed not only in the breast cancer tissues but also in the tumor-adjacent tissue compared to normal tissues, which may suggest that SVIP may also be expressed in stromal cells." (PMID 37408196, 2023). "Importantly, our data showed that SVIP mRNA expression was increased in all four intrinsic molecular subtypes of breast cancer (HER2+, triple negative (basal like), luminal A, and luminal B) compared to normal tissues using the GEPIA database." (PMID 37408196, 2023). "Here, epigenetic-associated transcriptional regulation of SVIP was investigated in breast tumors, and the promoter methylation level of SVIP in breast cancer was found to be significantly lower than in normal tissues, and SVIP mRNA expression was negatively correlated with SVIP methylation." (PMID 37408196, 2023). "Therefore, next, the estrogen dependency of SVIP expression in ER+ breast cancer cells was evaluated using 17β-estradiol (E2), and our results revealed that E2 did not cause any significant alterations in SVIP expression levels in MCF-7, T47D, and ZR75-1 cells." (PMID 37408196, 2023). "Interestingly, except for head and neck (50%), esophageal (23%), cervical (21%) cancers, and hematological malignancies (14%), particularly B cell lymphoma (33%), the SVIP promoter CpG island was most often found to be unmethylated in the other cancer types including prostate and breast cancers." (PMID 37408196, 2023). "SVIP protein expression was significantly higher in breast cancer cell lines compared to non-tumoral breast epithelial cell lines." (PMID 37408196, 2023). "Our results indicated that breast cancer cell lines present significantly higher SVIP expression compared to non-tumorigenic epithelial MCF-10A cell lines." (PMID 37408196, 2023).
glioblastoma (3 papers, 2019 to 2024). The most malignant astrocytic tumor (WHO grade IV). "In consistent with our previous finding, SVIP overexpression led to apoptosis in glioblastoma cell line U87MG34, it delayed the growth of HepG2 cells." (PMID 30683843, 2019). "In our study, SVIP expression levels were decreased and STUB1/CHIP expression levels were increased in glioblastoma, so that the two were out of balance compared with non-tumor tissues." (PMID 39138166, 2024).